CTSD (cathepsin D)
Diseases named in the same sentence as CTSD in open-access papers (continued):
Sharing a sentence is not in itself a finding about the gene and the disease.
COVID-19 (10 papers, 2021 to 2024). A disease caused by infection with severe acute respiratory syndrome coronavirus 2. "Among the peptides/proteins enriched in the COVID-19-positive group were multiple members of the cathepsin family including cathepsin B, cathepsin D, and cathepsin S." (PMID 39861814, 2024). "Conversely, the activity of cathepsin D was lower in the urine of the COVID-19-positive participant group and the activity of cathepsin B was comparable between the two groups." (PMID 39861814, 2024). "A predictor of poor clinical outcome in COVID-19 patients, CTSD is significantly affected by mdig knockout because mdig- cells exhibit decreased transcription of CTSD." (PMID 35021853, 2022). "In the case of COVID-19, there might be a hypothetical CTSD–OPN–Furin axis facilitating SARS-CoV-2 entry by accelerating the interaction between furin and the S protein." (PMID 35021853, 2022). "Increased levels of S100A8, MKI67, HSPA5, LYZ, CTSD, and IGHG1 were observed in COVID-19 patients." (PMID 39026676, 2024). "Indeed, most recent proteomic analysis of COVID-19 autopsies suggested an overall upregulation of the cathepsin family members, including CTSB, CTSD, CTSE, CTSH, CTSK, CTSS, and CTSZ, in the lung of the COVID-19 patients." (PMID 34335974, 2021). "We therefore measured the activities of matrix metalloproteinases (MMP2/9) and cathepsin D — proteases with known roles in endothelial injury — and found that MMP and cathepsin D activities are significantly increased in patients with COVID-19 compared with healthy donors." (PMID 34314391, 2021). "Additionally, plasma hyaluronidase activity was higher in the ICU COVID-19 patients vs. the non-ICU patients, and plasma MMP2, MMP9 and cathepsin D activities (enzymes which may cleave GAG-anchoring proteins) were significantly increased in COVID-19 patients vs. healthy controls." (PMID 35872762, 2022).
hepatocellular carcinoma (10 papers, 1991 to 2025). A malignant tumor that arises from hepatocytes. "After exposure to M1‐8, human hepatoma HepG2 cells rapidly co‐localized with lysosomes, disrupted lysosomal integrity, caused leakage of lysosomal protease cathepsin D, caspase activation and mitochondrial membrane potential changes; and promoted cell apoptosis." (PMID 36628597, 2023). "In line with this hypothesis, transfection of the dominant active RhoA into rat hepatoma cells was shown to induce the peripheral distribution of cathepsin D and of LIMPI-positive lysosomes, and the formation of stress fibers." (PMID 32111095, 2020).
Insulin resistance (10 papers, 2016 to 2025). Increased resistance towards insulin, that is, diminished effectiveness of insulin in reducing blood glucose levels. "CTSD has been implicated in the regulation of insulin-like growth factors (IGFs) bioavailability, a process strongly associated with the development of insulin resistance." (PMID 41480144, 2025). "Altogether, these data demonstrate that the metabolic parameter of type 2 diabetes (plasma FFA) is independently associated with plasma CTSD activity, linking plasma CTSD activity to insulin resistance via changes in FFA metabolism." (PMID 33101209, 2020). "Accordingly, we set out to investigate circulating cathepsin D concentrations and their associations with indexes of insulin resistance and clinical variables in normal individuals and newly diagnosed type 2 diabetic patients." (PMID 29375176, 2017). "Although the exact biological mechanism underlying the association between cathepsin D levels and insulin resistance and cardiovascular disease remains uncertain, it has attracted increasing interests." (PMID 29375176, 2017). "In accordance with previous evidence, our study has confirmed that cathepsin D levels were positively associated with insulin resistance." (PMID 29375176, 2017). "Cathepsin D was shown in a recent prospective study using two other cohorts to have a strong association with insulin resistance." (PMID 28846711, 2017). "Furthermore, previous reports have proven the ability of CTSD to proteolysis and influence the bioavailability of insulin-like growth factors (IGFs), factors that have been extensively linked to insulin resistance." (PMID 33101209, 2020). "Cathepsin D has been recently implicated in insulin resistance and cardiovascular disease." (PMID 29375176, 2017). "Therefore, cathepsin D may have clinical significance for the early identification of individuals at high risk of insulin resistance and cardiac dysfunction." (PMID 29375176, 2017). "Recently, altered circulating cathepsin D levels have been described in two large community cohorts with prevalent insulin resistance by using proximity extension assay." (PMID 29375176, 2017). "Our results showed that circulating cathepsin D concentrations were positively correlated with indexes of insulin resistance." (PMID 29375176, 2017). "Especially among newly diagnosed type 2 diabetic patients, cathepsin D were strongly correlated with insulin resistance." (PMID 29375176, 2017). "Further studies are required to elucidate the role of cathepsin D in the pathogenesis of insulin resistance and cardiac dysfunction." (PMID 29375176, 2017). "The dysregulation of extracellular matrix proteins like COL1A1 and CTSD suggests alterations in tissue remodeling processes and may contribute to the development of metabolic complications, such as insulin resistance and cardiovascular diseases." (PMID 38732002, 2024). "Thus, these evidences provide support for a potential functional metabolic link between insulin resistance and plasma CTSD activity." (PMID 33101209, 2020). "Notably, cathepsin D was suggested as a potential mediator that contributes to obesity, chronic inflammation, and insulin resistance through influenced detoxification of advanced glycation end products and proapoptotic protein activation." (PMID 29375176, 2017). "Thus, future studies will be needed to clarify the role of cathepsin D in the pathogenesis of insulin resistance." (PMID 29375176, 2017). "Moreover, the present study shows that circulating cathepsin D concentrations not only positively correlated with indexes of insulin resistance but also correlated with myocardial performance index." (PMID 29375176, 2017). "In addition, our results are in keeping with those of a very recent study describing cathepsin D as a marker of insulin resistance; moreover, cathepsin D expression is reduced in islets from people with type 2 diabetes." (PMID 28846711, 2017).
Insulin resistance (continued). "Therefore, with lipotoxicity as one of the key drivers for type 2 diabetes, CTSD might be an auspicious new player in the complex network contributing to insulin resistance by mechanisms that need to be further explored." (PMID 33101209, 2020). "Previous studies in patients demonstrated that plasma levels of cathepsin D (CTSD), which is optimally active in the acidic environment of lysosomes, correlate with insulin resistance." (PMID 33101209, 2020). "In newly diagnosed type 2 diabetes, a significant correlation was found between cathepsin D levels and HOMA-IR (homeostatic model assessment of insulin resistance) (r = 0.25, P = 0.01)." (PMID 29375176, 2017). "Importantly, recent data show that circulating levels of cathepsin D are increased in individuals with insulin resistance in nondiabetic community residents." (PMID 29375176, 2017).
Obesity (10 papers, 2016 to 2024). Accumulation of substantial excess body fat. "Interestingly, Ctsd, the gene encoding cathepsin D which is a critical lysosomal enzyme associated with lipid metabolism and obesity, was significantly increased in CD11b+CD45hi cells of WD-fed mice comparing that of CD-fed mice (FC = 1.38)." (PMID 31426806, 2019). "It is known that weight gain and obesity can activate cathepsin D and trigger the activation of pro-apoptotic proteins, by promoting mitochondrial dysfunction, followed by adipocyte death and oxidative stress induction." (PMID 31258482, 2019). "It has been suggested that CSTD acts a mediator between obesity and chronic adipose tissue inflammation as weight gain has shown to stimulate CTSD activity leading to adipocyte apoptosis, which is an important contributor to insulin resistance." (PMID 30670722, 2019). "It has been reported that key cathepsin, cathepsin D, is activated at the early stages of weight gain and obesity." (PMID 29375176, 2017). "It suggested that the chronic inflammation in obesity might interfere with the aseptic inflammation induced by the mechanical loading by the increase of vinculin, osteopontin, and cathepsin D." (PMID 36674516, 2023). "Therefore, we focused on cathepsin abnormalities, especially CTSL, CTSB and CTSD, as a mechanism of obesity-related lysosomal dysfunction in WAT and liver." (PMID 31357643, 2019). "Furthermore, the authors underscored preventive effects of a CTSD inhibitor on obesity-induced hepatic inflammation and disturbance in lipid metabolism in mice." (PMID 31357643, 2019).
pancreatic cancer (10 papers, 2014 to 2025). "In addition, fifteen of the proteins have been specifically linked to pancreatic cancer, including cathepsin D, glyceraldehyde-3-phosphate dehydrogenase, intercellular adhesion molecule 1, mesothelin, and tissue factor." (PMID 25987888, 2015). "The increased levels of CTSB/CTSD in cytosolic extracts confirmed the IMB-6G-induced LMP in pancreatic cancer cells." (PMID 28139733, 2017). "In a proteomic analysis, cathepsin D and its family member cathepsin B were identified as interacting partners of the anterior gradient 2 (AGR2) protein in pancreatic cancer cells and involved cell dissemination." (PMID 34439122, 2021). "Our results indicated that CTSD, DNAJB11, and PPT1 were not related with overall survival of pancreatic cancer (data not shown)." (PMID 27869176, 2016).
type 2 diabetes (10 papers, 2017 to 2025). "In line with the reduced plasma pH, plasma CTSD activity was significantly higher in male type 2 diabetic patients compared to male healthy individuals (p<0.001), suggesting that plasma CTSD activity is linked to type 2 diabetes progression." (PMID 33101209, 2020). "The observation that metabolic parameter (plasma FFA) related to type 2 diabetes associated with plasma CTSD activity (as dependent variable) in males implies an influence of this metabolic parameter on plasma CTSD activity." (PMID 33101209, 2020). "In the current study, we show that a metabolically-induced reduction of plasma pH in male type 2 diabetes patients correlates with increased plasma CTSD activity, which on its turn is linked to elevated plasma lipid and glucose levels." (PMID 33101209, 2020). "In the current study, our data are the first to report that the increased levels of circulating cathepsin D are associated with newly diagnosed and untreated type 2 diabetic patients." (PMID 29375176, 2017). "The present study provides the first evidence that increased levels of circulating cathepsin D are associated with newly diagnosed and untreated type 2 diabetic patients." (PMID 29375176, 2017). "Moreover, plasma CTSD activity also independently associated with a metabolic parameter of type 2 diabetes (plasma free fatty acids (FFA) in males)." (PMID 33101209, 2020). "Interestingly, correlation analysis revealed a positive association between cathepsin D levels and Tei index in type 2 diabetes (r = 0.22, P = 0.03)." (PMID 29375176, 2017). "Increased levels of circulating cathepsin D are closely linked with the presence of type 2 diabetes, and cathepsin D might serve as a novel biomarker for cardiac dysfunction in newly diagnosed type 2 diabetes." (PMID 29375176, 2017). "The activity of plasma CTSD was inversely associated with the whole-body sensitivity of insulin, i.e., the more likely it is that these overweight/obese individuals will develop type 2 diabetes (T2D), the higher the activity of their plasma CTSD." (PMID 36289617, 2022). "They found that CTSD protein levels were significantly boosted in the serum of the young patients (< 25 y) with type 2 diabetes as compared to the subjects with normal glucose tolerance." (PMID 33293479, 2020). "Firstly, Spearman’s correlation was performed to analyze the simple correlation between plasma CTSD levels/activity and metabolic parameters of type 2 diabetes (plasma FFA and insulin)." (PMID 33101209, 2020). "Our data therefore point for the first time toward plasma CTSD as a metabolic regulator in male type 2 diabetes." (PMID 33101209, 2020). "Recent studies suggested that plasma cathepsin D levels correlated with type 2 diabetic patients and moreover plasma cathepsin D activity is suggested as biomarker for hepatic insulin sensitivity." (PMID 32668602, 2020). "For this aim, plasma pH, plasma CTSD levels and activity as well as type 2 diabetes-related plasma parameters were measured in eighteen male type 2 diabetic patients and sixteen age-matched healthy males in the postprandial state." (PMID 33101209, 2020). "Nevertheless, our observations implying the functional role of CTSD as a metabolic regulator holds clinical value as it can lead to new ways to treat type 2 diabetes." (PMID 33101209, 2020). "It is also noteworthy to mention that in our cohort, it cannot be completely excluded that the increase in CTSD activity is due to the presence of other diseases that coincide with type 2 diabetes (such as NAFLD)." (PMID 33101209, 2020). "While in contrast to a previous study, we did not observe changes in plasma CTSD levels in type 2 diabetes patients, we observed that type 2 diabetes showed increased plasma CTSD activity, which also correlated metabolic parameters of type 2 diabetes." (PMID 33101209, 2020).
type 2 diabetes (continued). "In newly diagnosed type 2 diabetic patients, a highly significant correlation was found between cathepsin D levels and HOMA-IR (r = 0.25, P = 0.01)." (PMID 29375176, 2017). "This study was designed to investigate the relationship between cathepsin D and newly diagnosed type 2 diabetes." (PMID 29375176, 2017). "Newly diagnosed type 2 diabetic patients had significantly higher levels of cathepsin D in BMI, systolic blood pressure (BP), diastolic BP, total cholesterol, LDL cholesterol, and triglyceride than those in control subjects." (PMID 29375176, 2017). "Newly diagnosed type 2 diabetes demonstrated significantly higher circulating cathepsin D concentrations than controls (median level: 227 ng/ml versus 174 ng/ml, P < 0.01)." (PMID 29375176, 2017). "Altogether, these data show the potential of FFA to significantly impact the plasma pH, which might influence plasma CTSD activity in type 2 diabetes." (PMID 33101209, 2020). "Our data therefore point toward plasma CTSD as a metabolic regulator in male type 2 diabetes." (PMID 33101209, 2020). "Our data therefore point toward plasma CTSD as a novel metabolic regulator in type 2 diabetes." (PMID 33101209, 2020). "Considering its functions as a metabolic regulator, CTSD-related strategies to treat type 2 diabetes may provide a relevant alternative for these existing anti-diabetic agents." (PMID 33101209, 2020). "pH reductions in the interstitial fluid of diabetic patients therefore imply changes in plasma CTSD activity in type 2 diabetes, which might result in metabolic changes." (PMID 33101209, 2020). "In line with the finding that plasma CTSD activity was significantly higher in male type 2 diabetes compared with healthy males, we found that plasma CTSD activity positively correlated with HbA1c (%) (r = 0.577, p = 0.002), HOMA-IR (r = 0.398, p = 0.027) and plasma glucose (r = 0.465, p = 0.015)." (PMID 33101209, 2020). "In the current study, the identification of CTSD as a metabolic regulator might have implications for improving type 2 diabetes treatment." (PMID 33101209, 2020). "As plasma pH is slightly reduced in type 2 diabetic patients and we have previously shown that plasma CTSD activity is causally linked to insulin levels in vivo, it is likely that the activity of CTSD in plasma will be increased in type 2 diabetes compared to healthy individuals." (PMID 33101209, 2020). "Therefore, CTSD should be further investigated as a central metabolic regulator in the context of type 2 diabetes and potentially other metabolic diseases." (PMID 33101209, 2020). "These include LOAD risk-associated gene Cathepsin D (FDR = 4.9E−02), and Akt1 (FDR = 6.8E−04), a molecule that is activated in LOAD and is associated with LOAD risk in Chinese Han AD patients with type 2 diabetes." (PMID 28612290, 2017). "To validate this view, in the current study we investigated whether type 2 diabetic patients have increased plasma CTSD activity compared to healthy individuals and whether plasma CTSD levels and activity link to postprandial metabolic parameters of type 2 diabetes." (PMID 33101209, 2020). "In contrast, levels of plasma CTSD did not correlate with indicators of type 2 diabetes, including HbA1c (%), HOMA-IR and glucose." (PMID 33101209, 2020). "Furthermore, we observed that plasma CTSD activity, and not levels, significantly correlated with indicators of type 2 diabetes (plasma HbA1c, HOMA-IR and glucose) in males." (PMID 33101209, 2020). "Besides, plasma CTSD activity rather than levels significantly correlated with indicators of type 2 diabetes (HbA1c, HOMA-IR and glucose)." (PMID 33101209, 2020). "However, so far the interaction between CTSD activity and levels to postprandial metabolic derangements in type 2 diabetes is not known." (PMID 33101209, 2020).
type 2 diabetes (continued). "Another explanation for the lack of correlation between plasma CTSD levels and type 2 diabetes in the current study could be related to the known effect of estrogen in increasing CTSD expression as the previous report included both males and females, whereas all the subjects in our study are males." (PMID 33101209, 2020).
gastric cancer (9 papers, 2017 to 2025). A primary or metastatic malignant neoplasm involving the stomach. "In the present study, we found that overexpression of FOXM1 prompted cell migration and invasion of gastric cancer, and increased the expression of Cathepsin D (Cath-D)." (PMID 28978107, 2017). "For example, miR-185-3p directly targets CTSD in gastric cancer, and miR-3619 targets both CTSB and CTSD in their 3′ UTR sequence to negatively regulate their expression." (PMID 38611021, 2024).